BRINP3 (BMP/retinoic acid inducible neural specific 3)
Diseases named in the same sentence as BRINP3 in open-access papers:
BRINP3 is named in the same sentence as 29 diseases in open-access papers, as found by Europe PMC text mining. Sharing a sentence is not in itself a finding about the gene and the disease. The quoted sentences say what the papers report.
myocardial infarction (5 papers, 2008 to 2022). Gross necrosis of the myocardium, as a result of interruption of the blood supply to the area, as in coronary thrombosis. "The BRINP3 gene is reported to be correlated with the development of the nervous system, myocardial infarction, aggressive periodontitis, and osteoblast differentiation in genetic studies." (PMID 35845140, 2022). "Several studies have recently demonstrated a correlation between BRINP3 and human diseases including myocardial infarction, aggressive periodontitis, osteoblast differentiation, and tumor." (PMID 35845140, 2022).
Peri-Implantitis (5 papers, 2015 to 2025). An inflammatory process with loss of supporting bone in the tissues surrounding functioning DENTAL IMPLANTS. "This study provides evidence that the BRINP3 polymorphic variant rs1342913 and low level of BRINP3 expression are associated with peri-implantitis, independently from the presence of chronic periodontitis." (PMID 25887438, 2015). "To support the potential association of BRINP3 genes with the pathogenesis of chronic periodontitis and peri-implantitis, we investigated their expression in diseased and healthy peri-implant tissues." (PMID 25887438, 2015). "Statistically significant association between BRINP3 rs1342913 and peri-implantitis was found in both studied groups (p = 0.04)." (PMID 25887438, 2015). "G allele for BRINP3 rs1342913 also showed high prevalence in peri-implantitis group compared to chronic periodontitis only (p = 0.04)." (PMID 25887438, 2015). "This study provides evidence that BRINP3 polymorphic variants and low level of BRINP3 expression are associated with peri-implantitis, independently from the presence of chronic periodontitis." (PMID 25887438, 2015). "(ii) Does the genetic background associated to BRINP3 gene predispose to chronic periodontitis and peri-implantitis by the same way?" (PMID 25887438, 2015). "Our research group raised two questions: (i) Do BRINP3 polymorphisms predispose to peri-implantitis in patients with chronic periodontitis?" (PMID 25887438, 2015). "The E-protein post-transcriptionally represses the BRINP3/FAM5C vascular inflammatory gene, and the low level of BRINP3 expression may be associated with ulcerative colitis and peri-implantitis (inflammatory around Osseo-integrated dental implants)." (PMID 35723340, 2022). "Taking into consideration the association of BRINP3 rs1935881 and rs1342913 polymorphisms and the occurrence of peri-implantitis, we analyzed the association between BRINP3 markers and peri-implantitis in the replication sample based on groups divided according to peri-implant status." (PMID 25887438, 2015). "The TT genotype of BRINP3 rs1935881 was associated with peri-implantitis only (p = 0.04)." (PMID 25887438, 2015). "However, future studies are necessary, considering the BRINP3 function in vitro and in vivo and its association with bone loss response in separate cases of chronic periodontitis and peri-implantitis." (PMID 25887438, 2015). "In the present work, we looked for evidence that BRINP3 may contribute to peri-implantitis and chronic periodontitis by testing for association between genetic markers in BRINP3 and dental implant failure." (PMID 25887438, 2015). "GBP1 rs7911 and BRINP3 rs1935881 SNPs were found to be significantly more prevalent in patients with peri-implantitis." (PMID 41373620, 2025). "Motivated by the evidence that BRINP3 contributes to aggressive periodontitis we decided to investigate the role of BRINP3 in peri-implantitis." (PMID 25887438, 2015). "There is an excess of heterozygotes for the BRINP3 rs1342913 in cases with peri-implantitis (p = 0.04)." (PMID 25887438, 2015). "BRINP3 (exon 7–8 primers) expression was significantly higher in cases with diseased tissues (chronic periodontitis + peri-implantitis) compared to healthy tissues (p = 0.01)." (PMID 25887438, 2015). "In both BRINP3 experiments, lower expression was observed in peri-implantitis samples." (PMID 25887438, 2015). "Our genetic analysis suggests BRINP3 polymorphisms are related to the development of peri-implantitis even without chronic periodontitis as a risk factor for peri-implantitis development." (PMID 25887438, 2015). "The aim was to evaluate the association between single-nucleotide polymorphisms (SNPs) in genes involved in inflammation and bone metabolism (BMP-4, BRINP3, CD14, FGF-3, FGF-10, GBP-1, IL-1α, IL-1β, IL-10, LTF, OPG, and RANKL) and peri-implantitis." (PMID 41373620, 2025).
Peri-Implantitis (continued). "Based on our results, we can suggest that BRINP3 genotypes and expression are correlated to peri-implantitis, even without chronic periodontitis history." (PMID 25887438, 2015). "Indeed, lower levels of BRINP3 observed in mucosae from peri-implantitis only cases can reflect that peri-implantitis without interaction with chronic periodontitis history has different behaviors." (PMID 25887438, 2015).
periodontitis (5 papers, 2010 to 2025). An acute or chronic inflammatory process that affects the tissues that surround and support the teeth. "Research has also been directed at the genetic basis for susceptibility to peri-implant disease, analogous to studies that have linked genetic variants (e.g., in the BRINP3 gene) to periodontitis." (PMID 41584075, 2025). "The BRINP3 single nucleotide polymorphism rs1935881 was associated with norepinephrine change during exercise; the same BRINP3 variant we found to be associated to aggressive periodontitis in 389 subjects evaluated from 55 pedigrees." (PMID 25887438, 2015). "Since the original observation of an association between BRINP3 and aggressive periodontitis was made in a population data set enriched by Black families, it is possible that the detectable genetic effect of BRINP3 in dental implant failure is stronger in individuals of African heritage." (PMID 25887438, 2015). "In contrast, patients with both diseases showed significant higher BRINP3 gene expression, which can reflects the potential exacerbated reaction that BRINP3 can induct in the chronic periodontitis process." (PMID 25887438, 2015). "However, patients without chronic periodontitis history also can trigger a peri-implant bone loss despite the minimum BRINP3 mRNA expression." (PMID 25887438, 2015).
gastric cancer (3 papers, 2014 to 2022). A primary or metastatic malignant neoplasm involving the stomach. "Another study also showed that BRINP3 is an antioncogene in gastric cancer because of hypermethylation." (PMID 35845140, 2022). "BRINP3 is considered a novel tumor suppressor gene in tongue squamous cell carcinoma and might have similar biological functions in gastric cancer." (PMID 35845140, 2022).
osteosarcoma (2 papers, 2022 to 2024). A usually aggressive malignant bone-forming mesenchymal neoplasm, predominantly affecting adolescents and young adults. "Interacting in vitro with MAP4 (microtubule-associated protein 4) at the protein level, BRINP3 might promote the proliferation and invasion of osteosarcoma cells by upregulating MAP4 expression." (PMID 35845140, 2022). "We found in this study that BRINP3 was highly expressed in 64.13% of human osteosarcoma tissues and it was associated with histological grade, tumor recurrence, and poor clinical prognosis of osteosarcoma." (PMID 35845140, 2022). "As shown by our study results, BRINP3 might be utilized as a potential biomarker for diagnostic and therapeutic targets for osteosarcoma." (PMID 35845140, 2022). "Together, these results suggested that BRINP3 promotes cell proliferation, migration, and invasion in osteosarcoma." (PMID 35845140, 2022). "Consistently, our immunohistochemistry results showed relatively strong BRINP3 staining in the osteosarcoma tissues and a positive correlation between BRINP3 and the clinical prognosis of osteosarcoma." (PMID 35845140, 2022). "The results of this study show that BRINP3 not only expresses but also plays a critical role in osteosarcoma for the first time." (PMID 35845140, 2022). "In this study, a high level of BRINP3 expression was observed in human osteosarcoma and BRINP3 was correlated with tissue differentiation and clinical prognosis of osteosarcoma." (PMID 35845140, 2022). "In summary, our findings suggested that BRINP3 was overexpressed in human osteosarcoma and positively correlated with clinical prognosis." (PMID 35845140, 2022). "Considering the expression of BRINP3 in osteosarcoma cell lines, U2OS and Saos-2 cells were selected as the primary model for subsequent studies." (PMID 35845140, 2022). "BRINP3 was highly expressed in human osteosarcoma tissues and negatively correlated with the prognosis of osteosarcoma." (PMID 35845140, 2022). "In vitro, downregulation of BRINP3 was able to inhibit the proliferation and invasion of osteosarcoma cell lines." (PMID 35845140, 2022). "Subsequently, the role that BRINP3 plays in the regulation of osteosarcoma cell proliferation was examined using the Celigo cell counting assay and MTT assay for 5 days." (PMID 35845140, 2022). "BRINP3 was highly expressed in 64.13% of human osteosarcoma tissues and negatively correlated with the prognosis of osteosarcoma." (PMID 35845140, 2022). "Thus, our results demonstrated that BRINP3 promotes osteosarcoma progression possibly through the activation of MAP4." (PMID 35845140, 2022). "Next, we investigated whether upregulated MAP4 was involved in BRINP3-induced osteosarcoma progression in vitro." (PMID 35845140, 2022). "However, through in vitro experiments, we also found that the level of BRINP3 mRNA was inconsistent with the aggressiveness of osteosarcoma cell lines." (PMID 35845140, 2022). "BRINP3 downregulation might suppress the proliferation and invasion of osteosarcoma cells by inhibiting the expression of MAP4." (PMID 35845140, 2022). "Specifically, BRINP3 downregulation could inhibit the proliferation and invasion of osteosarcoma cell lines." (PMID 35845140, 2022). "Thus, in the present study, we evaluated bone differentiation-related gene BRINP3 expression in osteosarcoma and its role in the malignant progression of osteosarcoma." (PMID 35845140, 2022). "Our research also suggested that BRINP3 might be a potential target for anti-osteosarcoma strategies." (PMID 35845140, 2022). "In vitro, downregulation of BRINP3 could inhibit the proliferation and invasion of osteosarcoma cell lines." (PMID 35845140, 2022). "MAP4 could resist the inhibitory effect of downregulation of BRINP3 on the proliferation and invasion of osteosarcoma cells, suggesting that BRINP3 regulates the malignant progression of osteosarcoma cells at least partly through MAP4." (PMID 35845140, 2022).
osteosarcoma (continued). "Inhibition of BRINP3 could limit the proliferation and invasion of osteosarcoma cell lines, indicating the role of BRINP3 as an oncogene." (PMID 35845140, 2022). "Nonetheless, the role of BRINP3 in the progression of osteosarcoma remains unknown." (PMID 35845140, 2022). "Similarly, we found that BRINP3 could stimulate the proliferation and invasion of osteosarcoma by upregulating MAP4, suggesting that MAP4 might be related to the malignant progression of osteosarcoma." (PMID 35845140, 2022). "In addition, BRINP3 mRNA was expressed in human osteosarcoma cell lines." (PMID 35845140, 2022). "This supports that BRINP3 might play a role in human osteosarcoma tumorigenesis." (PMID 35845140, 2022). "However, the role that BRINP3 plays in the progression of osteosarcoma remains unknown." (PMID 35845140, 2022). "The Celigo and MTT assay data indicated that knockdown of BRINP3 suppressed the U2OS and Saos-2 cell proliferation rate on days 4 and 5, which attested to the inhibitory effect of BRINP3 knockdown on osteosarcoma cell proliferation." (PMID 35845140, 2022). "The results indicated that BRINP3 functions as an oncogene within osteosarcoma through MAP4 and thus could be used as a potential biomarker for the diagnosis and treatment of osteosarcoma." (PMID 38341398, 2024). "Overall, our results revealed that BRINP3 functions as an oncogene in osteosarcoma through MAP4 and might be a potential biomarker for diagnosis and therapeutic targets for osteosarcoma." (PMID 35845140, 2022). "Overall, our results demonstrate that BRINP3 functions as an oncogene within osteosarcoma through MAP4 and could therefore be used as a potential biomarker for osteosarcoma diagnostics and therapeutics." (PMID 35845140, 2022).
schizophrenia (2 papers, 2014 to 2020). A major psychotic disorder characterized by abnormalities in the perception or expression of reality. "Of 198 probes, we found one common probe between studies in the FAM5C (family with sequence similarity 5, member C) gene, also known as BRINP3, which showed significantly higher- DNA methylation changes in schizophrenia in both studies." (PMID 25206360, 2014).
tongue SCC (2 papers, 2014 to 2022). "The results suggest that the BRINP3 gene may be a novel tumor suppressor gene specific to tongue SCC." (PMID 35845140, 2022). "However, in tongue squamous cell carcinoma, FAM5C (BRINP3) has been found to act as a novel tumor suppressor gene." (PMID 35845140, 2022).
ulcerative colitis (2 papers, 2020 to 2022). An inflammatory bowel disease involving the mucosal surface of the large intestine and rectum. "Notably, BRINP3 (bone morphogenetic protein/retinoic acid inducible neural-specific 3), another component of the bone morphogenetic protein family identified in this study, was reported as being downregulated in the intestinal mucosa of patients affected by ulcerative colitis." (PMID 32183058, 2020).
Anxiety (1 paper, 2016). Intense feelings of nervousness, tension, or panic often arise in response to interpersonal stresses. "A pronounced phenotype was exhibited by male and female Brinp3−/− mice, which spent significantly longer on the open arms and center square, and less time in the closed arms, indicating reduced anxiety levels." (PMID 27826231, 2016). "The fact that both Brinp1−/− and Brinp3−/− mice exhibit this phenotype, along with sociability changes, may indicate a role for both genes in regulating anxiety as well as sociability." (PMID 27826231, 2016). "The reduced aversion of Brinp3−/− mice to the open arms of the Elevated Plus Maze demonstrates these mice have an altered response to potential danger: specifically, that the Brinp3−/− anxiety response is lessened." (PMID 27826231, 2016). "The observed changes in Brinp3−/− anxiety response, and increased Brinp2−/− locomotor activity may be relevant to the genetic variation at the 1q25.2 locus associated with patients diagnosed with ADHD, anxiety and other NDDs." (PMID 27826231, 2016). "An increase in open arm exploration was also apparent in the Brinp2/3−/− mice, consistent with the absence of Brinp3 alone, suggesting that this reduced anxiety phenotype is not modified by the absence of Brinp2." (PMID 27826231, 2016).
anxiety disorder (1 paper, 2016). A category of psychiatric disorders which are characterized by anxious feelings or fear often accompanied by physical symptoms associated with anxiety. "Future steps to investigate underlying physiology, as well as the use of fear response paradigms, such as fear avoidance and fear conditioning, may further elucidate the role of Brinp3 in relation to human anxiety disorders." (PMID 27826231, 2016).
bladder cancer (1 paper, 2022). "A deletion of the BRINP3 gene occurs in bladder cancer chromosome region candidate 1 (DBCCR1-like)." (PMID 35845140, 2022).
insomnia (1 paper, 2022). A sleep disorder characterized by difficulty in falling asleep and/or remaining asleep. "The loci harbouring SEMA3F and BRINP3 have similarly been reported for intelligence (SEMA3F46), general cognitive ability (SEMA3F40), educational attainment (SEMA3F47, BRINP341), insomnia (SEMA3F and BRINP342) and BMI (SEMA3F and BRINP3)." (PMID 35851147, 2022).
oral squamous cell carcinoma (1 paper, 2016). "In non-NDD diagnoses, overexpression of BRINP2 (FAM5b) or BRINP3 (FAM5c) has been implicated in cancer: BRINP2 is amplified in oral squamous cell carcinoma, and BRINP3 is overexpressed in pituitary adenomas." (PMID 27826231, 2016).
tumor (6 papers, 2016 to 2024). "Furthermore, the correlation analysis showed that BRINP3 expression was associated with clinicopathological features such as the histological grade, tumor recurrence, and prognosis." (PMID 35845140, 2022). "Nevertheless, the association between BRINP3 and tumor is controversial." (PMID 35845140, 2022). "BRINP3 participates in the differentiation of neuronal stem cells and overexpression was involved in the tumorigenesis of pituitary gonadotropin by increasing tumor cell proliferation, invasion, and metastasis." (PMID 35735600, 2023). "Currently, the role the BRINP3 protein plays in the tumor is still not well understood." (PMID 35845140, 2022). "In contrast to these findings, overexpression of BRINP3 is observed in pituitary gonadotrope cells and BRINP3 promotes tumor cell proliferation, migration, and invasion, suggesting that it might be a critical factor in pituitary tumorigenesis." (PMID 35845140, 2022). "BRINP3, however, has mainly been studied in non-neuronal tumour cells, and is also known as family with sequence similarity 5 member C (FAM5C)." (PMID 28630152, 2017).
cancer (5 papers, 2014 to 2023). A tumor composed of atypical neoplastic, often pleomorphic cells that invade other tissues. "Each successive layer expresses additional cancer marker genes – considering top-1 markers, coexpression hotspot 0 (CH0) expresses DEGS2; CH2 expresses BRINP3; CH10 expresses SUSD3; and CH19 expresses LOXL2." (PMID 37848426, 2023).
inflammation (2 papers, 2014 to 2022). Aberrant reaction of the microcirculation characterized by movement of fluid and leukocytes from the blood into extravascular tissues. "In vascular inflammation, inflammatory stimuli trigger the upregulated expression of BRINP3 through the NF-κB and JNK signaling pathways, and BRINP3 increases the mRNAs of leukocyte adhesion molecules through the ROS–NF-κB signaling pathway, thus enhancing monocyte adhesion to endothelial cells." (PMID 35845140, 2022).
neurodevelopmental disorder (1 paper, 2016). A behavioral and cognitive disorder with onset during the developmental period that involves impaired or aberrant development of intellectual, motor, or social functions. "In this study, the key aims were to determine the effect of loss of Brinp2 and/or Brinp3 on mouse anatomy and behavior, and to gain insight into the (potentially overlapping) function of these genes and their relationship with neurodevelopmental disorders." (PMID 27826231, 2016).
BRINP3 also shares sentences with these, for which no sentence is quoted: acute myocardial infarction (2 papers); aggressive periodontitis (2); atherosclerosis (2); cervical cancer (1); chronic periodontitis (1); coronary artery atherosclerosis (1); COVID-19 (1); depression (1); Infertility (1); periodontal diseases (1); pituitary adenomas (1); rheumatoid arthritis (1).